MIR200B (microRNA 200b)
Synonyms: hsa-mir-200b; MIRN200B; mir-200b
Gene: MicroRNA gene on chromosome 1 (1,167,104 to 1,167,198, forward strand). Ensembl gene ENSG00000207730.
Pathways (Reactome):
Immune System: Regulation of PD-L1(CD274) translation
Signal Transduction: Pre-NOTCH Transcription and Translation
Gene Ontology:
Biological process: miRNA-mediated post-transcriptional gene silencing
Cellular component: RISC complex
Homologues: Orthologues: chimpanzee MIR200B (96% identical), dog MIR200B (77% identical), guinea pig MIR200B (72% identical), tropical clawed frog xtr-mir-200b (72% identical), mouse Mir200b (69% identical), zebrafish mir200b (58% identical), zebrafish mir200c (57% identical). Paralogues in human: MIR200A (57% identical), MIR200C (45% identical).
Diseases named in the same sentence as MIR200B in open-access papers:
MIR200B is named in the same sentence as 6 diseases in open-access papers, as found by Europe PMC text mining. Sharing a sentence is not in itself a finding about the gene and the disease. The quoted sentences say what the papers report.
cervical cancer (1 paper, 2024). A primary or metastatic malignant neoplasm involving the cervix. "Evidence in the literature also indicates that PVT1 promotes cervical cancer progression by silencing MIR200B through EZH2 interaction, leading to histone H3K27 trimethylation and MIR200B inhibition." (PMID 39372928, 2024).
glioma (1 paper, 2020). A benign or malignant brain and spinal cord tumor that arises from glial cells (astrocytes, oligodendrocytes, ependymal cells). "The cancer genes MIR200A, MIR200B, and MIR429 in the different aberrant chromosomal region 1p36.33-p36.32 between tumor tissue (no aberration) and cell subpopulations (gain) have been described as implicated in regulation of tumor cell proliferation in glioma." (PMID 32634135, 2020).
lymphoid tumor (1 paper, 2022). "A total of six miRNA orthologs – MIR21, MIR30E, MIR106B, MIR10B, MIR200A, and MIR200B were identified as differentially expressed orthologs among mammary tumor cell lines, lymphoid tumor cell lines, and normal epithelial cell cultures (importance ≥10 and p≤0.01) (Figure-2)." (PMID 35765483, 2022).
mammary tumor (1 paper, 2022). "Similarly, several exosome-derived miRNA orthologs previously reported for increased expression in both canine and human mammary tumor cell lines, including MIR21, MIR106B, MIR181A1, MIR183, MIR200B, and MIRLET7G, were presented." (PMID 35765483, 2022).
cancer (2 papers, 2020). A tumor composed of atypical neoplastic, often pleomorphic cells that invade other tissues. "GRHL2 upregulates expression of the MIR141, MIR200A, MIR200B, MIR200C and MIR429 microRNAs by binding to their regulatory elements in a number of cancers." (PMID 32005677, 2020).
MIR200B also shares sentences with these, for which no sentence is quoted: tumor (2 papers).